PRDX3 (peroxiredoxin 3)
Diseases named in the same sentence as PRDX3 in open-access papers (continued):
Sharing a sentence is not in itself a finding about the gene and the disease.
ovarian carcinoma (7 papers, 2018 to 2025). A malignant neoplasm originating from the surface ovarian epithelium. "PRDX3 expression was associated with platinum resistance in ovarian cancer, and siRNA targeting of PRDX3 triggered cisplatin–induced apoptosis in SKOV3 ovarian cancer cells through suppression of the NF–κB signaling pathway." (PMID 30104402, 2018). "Additionally, increased PRDX3 mRNA expression was associated with poorer OS in all ovarian cancer patients treated with Platin, Taxol, and Taxol+Platin chemotherapy; PRDX3 also showed a poor PFS in all patients treated with Platin chemotherapy." (PMID 30104402, 2018). "In ovarian cancer, PRDX3 drives tumor progression by suppressing ROS accumulation and fostering ferroptosis resistance." (PMID 41049446, 2025). "Based on IPA analysis, 5 proteins, namely PKM, ANXA2, LGAL3, HNRNP1A1, PRDX3 and GAPDH, were found to be associated with the apoptosis signaling pathway in A2780 ovarian cancer cell line." (PMID 35163852, 2022). "ATP-a, PHB, and PRDX3 have been validated as mitochondrial proteins of ovarian cancer cells, and they were further confirmed through immunoblotting." (PMID 30736320, 2019). "In this study, immunohistochemistry analysis via HPA database showed that the expression of PRDX3 protein in ovarian cancer tissues was significantly up-regulated compared with normal ovarian tissues." (PMID 30104402, 2018). "High levels of PRDX3 mRNA were correlated to a poorer OS in grade III ovarian cancer patients, while PRDX3 predicted a better PFS in 37 patients with grade I ovarian cancer." (PMID 30104402, 2018). "Xu et al35 showed that PRDX3 mediated oxidative stress in ovarian cancer stem cells." (PMID 40757971, 2025). "Downregulation of PRDX3 enhances cisplatin-induced ovarian cancer cell apoptosis." (PMID 34623529, 2021). "Furthermore, the clinical stage results showed that high expression of PRDX3 mRNA was associated with a poorer OS in stages III and IV ovarian cancer patients." (PMID 30104402, 2018). "In addition, by using the KM plotter database, we found that increased PRDX3 expression was correlated with poorer OS in all ovarian cancer patients, especially for serous ovarian cancer patients." (PMID 30104402, 2018). "However, among the examined 9 ovarian cancer tissues, 8 cases had medium PRDX3 staining and 1 case had low PRDX3 staining." (PMID 30104402, 2018). "Based on our study, PRDX3 may predict a dismal prognosis in patients with ovarian cancer, particularly in those with poor differentiation and late-stage serous ovarian cancer." (PMID 30104402, 2018). "In addition, high PRDX3 levels predicted a poorer OS in grade III patients, stages III and IV patients, while PRDX3 predicted a better PFS in 37 patients with grade I ovarian cancer; this finding might have been due to the small and unbalanced sample sizes." (PMID 30104402, 2018). "Elevated expression of PRDX3, PRDX5, and PRDX6 mRNAs showed poorer overall survival (OS); PRDX5 and PRDX6 also predicted poor progression-free survival (PFS) for ovarian cancer patients." (PMID 31315664, 2019). "Meanwhile, elevated expression of PRDX3, PRDX5, and PRDX6 mRNAs showed poorer overall survival (OS); PRDX5 and PRDX6 also predicted poor progression-free survival (PFS) for ovarian cancer patients." (PMID 30104402, 2018). "According to our results, high levels of PRDX3, PRDX5, and PRDX6 indicated poor clinical outcomes in ovarian cancer." (PMID 30104402, 2018). "Increased PRDX3 mRNA expression was found to be related to a poorer OS in all ovarian cancer patients and serous ovarian cancer patients, but not in endometrioid cancer patients." (PMID 30104402, 2018). "Taken together, these observations indicated that PRDX3, PRDX5, and PRDX6 overexpression could lead to the chemotherapy resistance in ovarian cancer and therapeutic strategies targeting these isoforms may therefore be an effective anticancer therapy for ovarian cancer." (PMID 30104402, 2018).
ovarian carcinoma (continued). "However, there are no reports concerning the prognostic value of either PRDX3 protein or mRNA in ovarian cancer." (PMID 30104402, 2018).
Insulin resistance (6 papers, 2018 to 2025). Increased resistance towards insulin, that is, diminished effectiveness of insulin in reducing blood glucose levels. "On the other hand, in the adipocyte insulin resistance of obese mice and humans, antioxidant peroxiredoxin 3 (Prdx3) decreases significantly." (PMID 36976988, 2023). "A systemic knockdown of PRDX-3 in mice leads to oxidative stress, increased accumulation of white adipose tissues, dysregulated adiposity, and systemic insulin resistance." (PMID 30302116, 2018). "Taken together, these data suggest that lower mitochondrial CoQ accelerates superoxide generation, most likely from complex II, which in turn elevates the mitochondrial H2O2 burden, promotes PRDX3 dimerisation and drives insulin resistance." (PMID 29402381, 2018). "In contrast, overexpression of PRDX-3 can reduce the levels of oxidative stress and alleviate insulin resistance, highlighting that oxidative stress plays a key role in maintaining insulin sensitivity." (PMID 30302116, 2018). "In addition, Rha treatment modulated insulin resistance and increased gene expression of antioxidant enzymes (Cat, Sod2, Gpx3, Mgst1, Prdx3, Gsta4, Gsr, and Sod1) in the ovaries of the PCOS rats." (PMID 35663203, 2022). "We next established the dose of MitoPQ that specifically induced PRDX3 dimerization without affecting cytosolic PRDX2 in 3T3-L1 adipocytes treated with MitoPQ for 2 h to mimic the subcellular oxidative burden in insulin resistance." (PMID 29599292, 2018).
liver fibrosis (6 papers, 2023 to 2025). "These discoveries not only elucidate a novel mechanism underlying liver fibrosis caused by schistosomiasis but also identify the miR-383-5p/PRDX3 pathway as a promising therapeutic target for antifibrotic interventions." (PMID 40462224, 2025). "PRDX3 silencing exacerbates liver fibrosis and HSC activation, while HSC overexpression of PRDX3 alleviates liver fibrosis caused by CCl4 by inhibiting HSC activation through the mitochondrial ROS/TGF-β1/Smad2/3 signalling pathway." (PMID 40462224, 2025). "Liver fibrosis is increased in Prdx3 (peroxiredoxin 3) knockdown mice; however, mutation of three m6A sites in the Prdx3 transcript resulted in a loss of YTHDF3-mediated down-regulation of PRDX3 protein, thus increasing PRDX3." (PMID 37628704, 2023). "Oxidative stress can be detected in other liver fibrosis models, and the expression of PRDX3 and amount of ROS in the livers of mice infected with S. japonicum were significantly increased in our study." (PMID 40462224, 2025). "This study elucidates the role of the miR-383-5p/PRDX3 axis in schistosomiasis-induced liver fibrosis, suggesting that PRDX3 is a potential therapeutic target for this disease." (PMID 40462224, 2025). "A significant increase in the area of single egg granulomas and surrounding collagen fibres suggested an exacerbation of liver fibrosis in PRDX3 knockout mice." (PMID 40462224, 2025). "This assumption was confirmed via overexpression of miR-383-5p using the AAV8 vector system in mice, which downregulated PRDX3 expression, leading to elevated hepatic ROS levels and subsequent promotion of liver fibrosis." (PMID 40462224, 2025). "This study demonstrated that miR-383-5p negatively regulates PRDX3 expression in S. japonicum-infected mice, contributing to exacerbated liver fibrosis." (PMID 40462224, 2025). "Our study elucidates the role of the miR-383-5p/PRDX3 axis in schistosomiasis-induced liver fibrosis and identifies PRDX3 as a promising therapeutic target for this disease." (PMID 40462224, 2025). "Additionally, knockout mice were used to confirm that PRDX3 alleviates liver fibrosis induced by schistosomiasis through scavenging ROS." (PMID 40462224, 2025). "Therefore, we believe that miR-383-5p plays a role in schistosomiasis-liver fibrosis by regulating the expression of PRDX3 and affecting the oxidative stress of HSCs." (PMID 40462224, 2025). "In addition, a recent study revealed that the m6A reader YTHDF3 can influence TGF-β signaling pathway by mediating peroxiredoxin 3 translation in liver fibrosis." (PMID 37434186, 2023). "What’s more, YTHDF3 directly regulates peroxiredoxin 3 (PRDX3) translation in an m6A-dependent manner, thereby reducing hepatic stellate cell (HSC) activation and liver fibrosis in response to mitochondrial oxidative stress." (PMID 36830642, 2023).
medulloblastoma (6 papers, 2020 to 2025). A malignant, invasive embryonal neoplasm arising from the cerebellum. "What’s more, PRDX2, as a target of miR-200b-3p, promoted the proliferation, invasion and EMT of colorectal cancer cells; PRDX3, as a target molecule of miR-383, regulated the growth of medulloblastoma cells." (PMID 33771165, 2021). "MiR-383 overexpression decreased cell growth and increased apoptosis through negative regulation of PRDX3 in medulloblastoma." (PMID 34199590, 2021). "Changes of PRDX3 are also observed in medulloblastoma where miR-383 is underexpressed." (PMID 34199590, 2021).
myocardial infarction (6 papers, 2013 to 2025). Gross necrosis of the myocardium, as a result of interruption of the blood supply to the area, as in coronary thrombosis. "Previous study found that PRDX3 knockout aggravated myocardial fibrosis and ventricular remodeling after myocardial infarction in mice." (PMID 38195664, 2024). "The overexpression of Prdx3 was found to protect the heart against left ventricular remodelling and failure after myocardial infarction." (PMID 37371917, 2023). "The proteomics analysis showed that peroxiredoxin-3 in SBP protects against oxidative stress in a rat model of myocardial infarction." (PMID 34900089, 2021). "For instance, the overexpression of PRDX3, a mitochondrial antioxidant, prevents LV remodeling and failure after myocardial infarction in mice." (PMID 24303125, 2013). "A recent study reported that the overexpression of Prdx3 protects the heart against left ventricular remodeling and failure after myocardial infarction (MI)." (PMID 34439492, 2021).
cervical cancer (5 papers, 2012 to 2025). A primary or metastatic malignant neoplasm involving the cervix. "In cervical cancer, single nucleotide polymorphism of Prdx3 leads to significant increased risk of cervical cancer and progression." (PMID 31500275, 2019). "In summary, these data suggest involvement of two genes, RSP19 and PRDX3, or other SNPs in linkage disequilibrium, with cervical cancer risk." (PMID 22496757, 2012). "The mitochondrial peroxidases, Prdx3 and Prdx4, were found to display expression changes in bladder cancer that related to disease prognosis, and Prdx3 upregulation was associated with increased cervical cancer risk; H2O2-induced Prdx3 overexpression was observed in the eye lens in cataractogenesis." (PMID 24876913, 2014). "Our data indicated that the conditioned medium from the PRDX3-overexpression CCa cells strongly promoted tube formation of HLECs, whereas PRDX3 knockdown impaired the ability of cervical cancer cells to induce HLEC tube formation." (PMID 41049446, 2025). "In addition, gene expression analysis has revealed the increase in the expression of Prdx3 in cervical cancer." (PMID 31500275, 2019).
lung carcinoma (5 papers, 2011 to 2026). "High PRDX3 expression was independently associated with significantly poorer clinical prognosis in lung cancer, particularly in the LUAD subtype." (PMID 42092925, 2026). "Peroxiredoxin 3 (PRDX3), a well-characterized ferroptosis biomarker, has been implicated in lung cancer progression." (PMID 42092925, 2026). "Collectively, PRDX3 represents a promising independent prognostic biomarker for lung cancer, especially for LUAD, and a potential therapeutic target for ferroptosis-based and immunotherapeutic strategies." (PMID 42092925, 2026). "The mRNA levels of PRDX1, PRDX2, PRDX3, PRDX5, and PRDX6 showed an excellent correlation with the OS of lung cancer patients." (PMID 32908916, 2020).
Ataxia (4 papers, 2022 to 2025). Ataxia refers to impaired coordination of voluntary muscle movement. "More recently, two further families carrying novel homozygous PRDX3 variants were identified, following a screen of >3,500 ataxia exomes." (PMID 37553803, 2023). "Subsequently, a novel homozygous PRDX3 variant was reported in a patient with infantile‐onset severe cerebellar ataxia and peripheral neuropathy, expanding the disease's clinical spectrum." (PMID 37553803, 2023). "Clinical spectrum of all reported patients with PRDX3‐associated cerebellar ataxia." (PMID 37553803, 2023). "In addition, there was a third report that associates a PRDX3 non‐sense variant p.Lys166* with cerebellar ataxia and profound hearing impairment." (PMID 37553803, 2023). "This case broadens the phenotypic spectrum of PRDX3-related disease, highlights its genetic and clinical heterogeneity, and reinforces the importance of early genetic testing in paediatric ataxia." (PMID 41351775, 2025). "Our findings not only contribute to a better characterization of the disease but also highlight the need for increased awareness of PRDX3 disease in undiagnosed cerebellar ataxia patients." (PMID 37731903, 2023). "Eleven patients showed very early-onset ataxia and CA with cortical hyperintensities caused by mutations in ITPR1, KIF1A, SPTBN2, PLA2G6, PMPCA, and PRDX3." (PMID 36233161, 2022).
diabetes (4 papers, 2013 to 2018). "In addition, PRDX-3 transcription is downregulated in adipose tissues in obese and insulin-resistant humans, while some studies have shown that diabetics are associated with increased levels of oxidative stress markers such as lipid peroxidation." (PMID 30302116, 2018).
glioma (4 papers, 2022 to 2025). A benign or malignant brain and spinal cord tumor that arises from glial cells (astrocytes, oligodendrocytes, ependymal cells). "In glioma, lnc-NLC1-C (narcolepsy candidate region one gene C) promotes glioma cell proliferation, migration and invasion and inhibits autophagy via lnc-NLC1-C/miR-383/PRDX-3 axis." (PMID 38933333, 2024).
Sepsis (4 papers, 2017 to 2024). Sepsis is defined as life-threatening organ dysfunction caused by a dysregulated host response to infection. "At enrollment, sepsis was associated with significant increases in the expression of mRNAs related to redox metabolism (myeloperoxidase, 64-fold; PRDX3, 2.6-fold; SOD2, 2.2-fold) and redox-responsive genes (FOXM1, 21-fold; SELS, 16-fold; GLRX2, 3.4-fold)." (PMID 29540208, 2018). "Our findings indicated that targeting metabolic reprogramming through PRDX3 to alleviate ROS accumulation and induce M2 macrophage polarization might be an effective treatment of sepsis-associated ALI." (PMID 38431661, 2024). "To determine the role of PRDX3 in macrophage polarization during sepsis, we first assessed the expression of PRDX3 in murine endotoxemia and sepsis models." (PMID 38431661, 2024). "In models of murine sepsis and endotoxemia, the expressions of the PRDX3 gene and protein were decreased in lung tissues." (PMID 38431661, 2024). "To further understand the effect of PRDX3 on macrophage polarization during sepsis, we overexpressed PRDX3 in RAW 264.7 cells with lentivirus carrying PRDX3 cDNA (Adv-PRDX3), and incubated the stable overexpression cells in medium with both LPS and IFN-γ." (PMID 38431661, 2024). "Although little is known about the possible involvement of Prdx3 in sepsis, there are examples of inflammasome regulation and inflammatory cell death by Prdx3." (PMID 35052630, 2022). "There are few reports showing the involvement of Prdx3 in the etiology of sepsis, although there is one report that Prdx3 mRNA can be found among the 84 mRNAs whose levels in exosomes are higher in patients suffering from sepsis than in healthy controls." (PMID 35052630, 2022). "In this study, we hypothesized that macrophage polarization participates in sepsis-induced lung injury and examined the mechanism and function of PRDX3 in this pathological process." (PMID 38431661, 2024). "In this study, we demonstrated that macrophage polarization occurs in sepsis-associated ALI and is accompanied by mitochondrial dysfunction and inflammation, and a decrease of PRDX3 promotes the initiation of macrophage polarization and mitochondrial dysfunction." (PMID 38431661, 2024). "PRDX2 deficiency as well as PRDX3 deficiency were increased LPS-induced septic shock in mice, and circulating PRDX4 level was reported as oxidative stress marker in patient with sepsis." (PMID 28881633, 2017). "However, the potential role of PRDX3 in sepsis has not been clarified, and the mechanism of PRDX3 in macrophage polarization requires study." (PMID 38431661, 2024).
benign prostatic hyperplasia (3 papers, 2017 to 2025). A non-cancerous nodular enlargement of the prostate gland. "Prdx3 has been reported to promote pyroptosis in benign prostatic hyperplasia (BPH) and also act as a suppressor of pyroptosis by inhibiting NLRP3 inflammasome activation." (PMID 38007535, 2023). "Therefore, within this complex network of mechanisms, it becomes evident that inhibiting Prdx3 represents a potential strategy to prevent further prostatic hyperplasia." (PMID 40837016, 2025). "Benign prostatic hyperplasia (BPH) is driven by hormonal and inflammatory mechanisms, yet emerging factors such as peroxiredoxin 3 (Prdx3), oxidative stress (OS), pyroptosis, and autophagy remain understudied." (PMID 40837016, 2025).
colorectal cancer (3 papers, 2017 to 2025). A primary or metastatic malignant neoplasm that affects the colon or rectum. "In colorectal cancer, upregulation of PRDX3, induced by forkhead box M1 (FOXM1), could stimulate tumor cells to multiply and metastasize to distant locations by mitochondrial dysfunction." (PMID 41049446, 2025).
endometrial cancer (3 papers, 2017 to 2020). Primary or metastatic malignant neoplasm involving the endometrium (mucous membrane that lines the endometrial cavity). "A high expression of Prdx3 is associated with endometrial cancer and it has the potential to serve as a prognostic marker for endometrial cancer; thus, it can be targeted for the development of better therapeutic strategies." (PMID 31500275, 2019). "Like Prdx3, the expression of Prdx5 is upregulated in endometrial cancer and this enhanced expression of Prdx5 in the endometrium of females with endometrial tumor can serve as a prognostic marker." (PMID 31500275, 2019).
insulinoma (3 papers, 2021 to 2022). "However, over expression of PRDX3 in RINm5F insulinoma cells protects against death induced by hydrogen peroxide delivered as a bolus." (PMID 34557160, 2021). "In insulinoma, INS-1 cells of rats and human beta cells (1.1B4) and high-glucose settings induce acetylation of peroxiredoxin-3 (PRDX3) which is a mitochondrial protein with antioxidant function and acts as ROS scavengers." (PMID 36465704, 2022).
malignant mesothelioma (3 papers, 2014 to 2019). A malignant neoplasm of the pleura or peritoneum, arising from mesothelial cells. "The upregulated expression of Prdx3 is also observed in malignant mesothelioma (MM) cells and an overexpression of Prdx3 in MM cells maintains a redox set point that enables these cells to survive in conditions with elevated levels of mitochondrial ROS." (PMID 31500275, 2019).
melanoma (3 papers, 2012 to 2018). A malignant, usually aggressive tumor composed of atypical, neoplastic melanocytes. "For example, melanoma cell lines have been grouped into two categories based on the expression of anti-apoptotic and anti-oxidant genes, including PRDX3." (PMID 22761781, 2012).